HNRNPA1 (heterogeneous nuclear ribonucleoprotein A1)
Diseases named in the same sentence as HNRNPA1 in open-access papers (continued):
Sharing a sentence is not in itself a finding about the gene and the disease.
tumor (continued). "Further analysis revealed that the upregulation of hnRNPA1 in HNC was closely related to increased tumor size, lymph node metastasis, advanced tumor stage, and chemoresistance." (PMID 30642385, 2019). "hnRNPA1 mediates its anti-tumor effects in part by controlling mRNA export and mRNA translation of anti-apoptotic proteins XIAP and BCL-XL." (PMID 31480735, 2019). "hnRNPA1, the most ubiquitously expressed member of the hnRNP protein family, contributes to tumor development and progression." (PMID 31480735, 2019). "Regulation of the hnRNPA1 RNA-binding protein by either miR-15a-5p or miR-25-3p leads to increased tumor growth by inhibiting the biogenesis of miR-18a-3p, an inhibitor of the K-RAS oncogene." (PMID 28904816, 2017). "Consistent with the experiment in vitro, estradiol reduced MDM2 expression through elevating the level of hnRNPA1 in A375 tumor tissue." (PMID 28035066, 2017). "Our data predicted that the estradiol stimulate tumor apoptosis by elevating the level of hnRNPA1, and then influenced MDM2 expression in different types of cell lines." (PMID 28035066, 2017). "Specifically, the disruption of hnRNPA1 function is necessary for the expression/translocation of ICD markers in SK-treated tumor cells." (PMID 27248319, 2016). "The oncogene c-Myc and hnRNPA1 had been showed have a strong impact on the expression of PKM2 in tumor cells." (PMID 26745603, 2016). "Our in vitro data suggest that the coordinated over-representation of both S6K2 signalling and hnRNPA1 in tumours would be the optimal combination to stimulate IRES-mediated translation." (PMID 25324306, 2014). "Similarly, in lung adenocarcinoma, ESCO2-mediated acetylation of HNRNPA1 contributes to metabolic reprogramming and tumor progression." (PMID 41275207, 2025). "hnRNPA1 can also suppress tumor progression, inhibiting metastasis in gastric cancer." (PMID 39885614, 2025). "Additionally, in vivo studies using orthotopic xenograft GBM models confirmed that the expression of 3 C protein reduces the level of hnRNPA1 and induces apoptosis in tumor cells." (PMID 40340965, 2025). "HNRNPA1 is correlated with immunosuppressive status of the tumor immune microenvironment." (PMID 40046063, 2025). "We confirmed several of our DSGs in mouse tumours, including Hnrnpa1, Srpk1, Hnrnpc, and Mlx." (PMID 39313128, 2024). "This suggests the indispensability of the R194 residue for tumor-promoting function of HNRNPA1." (PMID 39341825, 2024). "BET antagonists reduce cellular proliferation and suppress tumor development by reducing hnRNPA1." (PMID 38690008, 2024). "Moreover, hnRNPA1 was also involved in the packaging of lncFERO into exosomes in GC cells; upregulation of hnRNPA1 expression in GCSCs induced GC cells to secrete lncFERO, which increased tumor stemness and chemoresistance." (PMID 37436087, 2023). "Interestingly, some studies have shown that hnRNPA1 can promote tumor metastasis and EMT, while others drawn completely opposite conclusions." (PMID 35814393, 2022). "Previous studies have shown that hnRNPA1 may regulate tumor metastasis by regulating EMT-related molecules, so we sought to determine whether hnRNPA1 regulates NSCLC metastasis through regulating the EMT process." (PMID 35814393, 2022). "In this study, we verified HNRNPA1 as a tumor driver gene for PTC for the first time." (PMID 35022405, 2022). "Moreover, we observed that 21 splicing factor genes showed significantly differential AS between SS and tumor-adjacent tissues, such as HNRNPA1, PTBP2, QKI, RBFOX2, and TRA2A." (PMID 36118864, 2022). "Additionally, AC elevated the expressions of miR-635, E-cadherin, GRP78, and Chop and inhibited Ki-67, HMGA1, N-cadherin, and hnRNPA1 expressions in tumor tissues of mice." (PMID 35692504, 2022). "Moreover, the patients with LN metastasis or advanced tumor stage had higher serum EV-packaged hnRNPA1, SAE1, and PROX1 expression levels." (PMID 35579947, 2022).
tumor (continued). "That is to say, sEV-miRNAs loaded by hnRNPA1 promote tumor proliferation and migration." (PMID 34222256, 2021). "Moreover, the HNRNPA1 expression was downregulated compared with those in tumor tissues from sh‐NC group." (PMID 32052594, 2020). "We also checked the RP11‐81H3.2 and HNRNPA1 expression in tumor tissues." (PMID 32052594, 2020). "Finally, the role of USP7/hnRNPA1/miR-522 axis in affecting tumor growth and chemotherapeutic efficacy were evaluated in vivo." (PMID 32106859, 2020). "Moreover, for the first time, we demonstrate that Quercetin, which suppresses hnRNPA1, can also enhance the anti-tumor effects of BET inhibitors in vitro and in vivo." (PMID 31480735, 2019). "Importantly, we show co-expression of hnRNPA1 with the BET protein BRD4 (Bromodomain-containing protein 4) in human tumor samples." (PMID 31480735, 2019). "In summary, this study has revealed that HNRNPA1 promotes cell growth via exosomal sorting of tumor suppressive miRNAs (mainly miR-320) in CML, while the secreted exosomes in turn function to remodel the niche to a leukemic favorable microenvironment via inhibiting osteogenesis of BMMSC." (PMID 31534508, 2019). "We subsequently identified the effective role of CAF-derived hnRNPA1 in tumor growth in vivo." (PMID 30642385, 2019). "Our results indicated that GZZSZTW significantly increased the expression levels of multiple genes involved in promoting cell proliferation, most of which are highly expressed in tumor cells, such as Tnfaip2, Chi3l1, Tnf, Pfkfb3, Sox8, Jag1, Mafb, Pla2g7, Hnrnpa1, and E2f3." (PMID 30275866, 2018). "We hypothesize that there is a circuit of miRNAs’ regulation between oncogenic and tumor-suppressor miRNAs, through direct modulation of hnRNPA1 expression." (PMID 28904816, 2017). "Based on these findings, we therefore also considered the possibility that the dysfunction of hnRNPA1 may play a key role in generation of tumor immunogenicity." (PMID 27248319, 2016). "Alternatively, it may be due to microenvironmental factors or the instability of HNRNPA1 in a large tumor mass." (PMID 27282379, 2016). "Consistently, overexpression of hnRNPA1 in 4T1 cells (SK-4T1(hn)-TCL) also reversed the tumor immunogenicity of TCL-pulsed DCs (SK-4T1(hn)-TCL-pulsed DCs) and the treatment decreased the survival rate of test mice, as compared with mice treated with SK-TCL-pulsed DCs." (PMID 27248319, 2016). "Similarly, overexpression of hnRNPA1 in 4T1 tumor cells also reversed the protein translocation process of CRT molecules in response to SK." (PMID 27248319, 2016). "Moreover, MYC has been shown to increase hnRNPA1 expression leading in turn to higher expressing of pyruvate kinase, contributing to aerobic glycolysis frequently observed in tumor cells." (PMID 27303665, 2016). "Interestingly, although several studies have shown that hnRNPA1 can inhibit tumor proliferation and metastasis and that hnRNPA1 may act as an antitumor factor during tumorigenesis, other studies have reached the opposite conclusion." (PMID 38268030, 2024). "Additionally, hnRNPA1 was involved in tumor immune responses as well." (PMID 35879279, 2022). "Western blot assays showed that hnRNPA1 depletion inhibited the expression of E-cadherin and promoted the expression of N-cadherin and Vimentin, which suggested that hnRNPA1 might promote tumor metastasis by accelerating the transition of mesenchymal phenotypic in NSCLC." (PMID 35814393, 2022). "Therefore, a possible combination of VEGF-C, KRAS and hnRNPA1 inhibitors could enhance an inhibitory effect on the tumor-induced lymphangiogenesis." (PMID 35838046, 2022). "Moreover, sEV-miRNAs loaded by hnRNPA1 facilitated tumor proliferation and migration." (PMID 34222256, 2021). "Finally, we confirmed that hnRNPA1-loaded sEV-miRNAs could facilitate tumor proliferation and migration based on database analysis and cytological experiments." (PMID 34222256, 2021). "In addition, in contrast to SRSF1, hnRNPA1 exclusively localized in tumor nuclei." (PMID 34065983, 2021).
tumor (continued). "However, hnRNPA1 may also contribute to other factors into exosome in EMT CRC cells which can regulate tumour blood vessel permeability, and how hnRNPA1 mediated the package into EMT‐CRC cells‐derived exosomes is still need fully elucidated." (PMID 34936736, 2021). "The oncogenic effect of HNRNPA1 and HNRNPAB is of great interest to understand the underlying mechanisms of alternative splicing in carcinogenesis, which might provide novel insights into anti‐tumour therapy." (PMID 32915499, 2020). "Moreover, fluorescence in situ hybridization (FISH) assays revealed that miR-196a expression in tumor cells was greater when hnRNPA1 expression was upregulated in the nearby CAFs, whereas suppressing hnRNPA1 expression in CAFs resulted in a low miR-196a signal in tumor cells." (PMID 30642385, 2019). "HnRNPA1, an hnRNP family member, regulate glycolysis by producing the PKM2 isoform, promoting tumor growth in multiple cancers." (PMID 39885614, 2025). "Glycolysis-induced lactate production promoted P300-mediated lactylation of HNRNPA1 at lysine 350, which facilitated PKM pre-mRNA splicing toward the PKM2 isoform, enhancing glycolytic flux and supporting tumor growth." (PMID 41275207, 2025). "When HNRNPA1 cannot be lactylated, the balance of PKM splicing shifts, resulting in more PKM1 and less PKM2, which in turn dampens glycolytic flux and tumor growth." (PMID 41275207, 2025). "In HNRNPA1-K350R cells, forced expression of PKM2 significantly increased cell proliferation and partially restored tumor growth." (PMID 41275207, 2025). "In contrast, long non-coding RNAs (lncRNAs) are known to modulate tumor metastasis and epithelial-mesenchymal transition (EMT) by interacting with hnRNPA1 and miRNAs." (PMID 39834948, 2024). "The translational efficiency of VRK1 mRNA is increased by its binding to the 3’-untranslated region of hnRNPA1, and thus potentiates the expression of CCND1 (cyclin D1) mediated by phosphorylation of CREB, which promotes lung cancer tumor cell proliferation." (PMID 38753965, 2024). "Studies have shown that cisplatin and paclitaxel activate the USP7/hnRNPA1 axis to promote CAF secretion of miR-522, which inhibits the activity of ALOX15 in tumor cells, reduces ROS production, and inhibits ferroptosis in tumor cells." (PMID 39769177, 2024). "The overexpression of heterogeneous nuclear ribonucleoprotein A1 (HNRNP A1) has been observed to enhance the proliferation, migration, and invasion of HCC cells, promoting tumor growth, and delaying senescence." (PMID 37436087, 2023). "AC also suppressed the expression of Ki-67, HMGA1, N-cadherin, and hnRNPA1 and enhanced the expression of E-cadherin, GRP78, and Chop in tumor tissues." (PMID 35692504, 2022). "We also find that hnRNPA1 can directly regulate the exon skipping of LAS1L exon 9, which further promote the tumor metastasis and EMT transition." (PMID 35814393, 2022). "In this study, we reported for the first time that miR-646 is inversely related to HNRNPA1 expression, suppresses PTC proliferation and metastasis, and promotes tumor apoptosis." (PMID 35022405, 2022). "Other two high-ranking hub proteins (HNRNPA1 and VEGFA) were also proved to play a vital role in tumor cell biology." (PMID 36147313, 2022). "Longer OS was observed in tumor-bearing mice transplanted with USP7-KD, hnRNPA1-KD, and lncFERO-KD cells." (PMID 34845198, 2021). "A paired analysis of tumor and adjacent tissues from patients with NSCLC for expression of several hnRNPs showed that in particular hnRNPA1 expression was frequently increased (i.e., more than 2-fold in 16/21 cases)." (PMID 34065983, 2021). "Scenario 3 included hnRNPA1 expression, preoperative PSA, clinical tumor stage (cT stage), and Gleason score obtained on the prostatectomy specimen." (PMID 32417965, 2020). "Significantly, Quercetin decreased hnRNPA1 in vivo and enhanced the effects of BET inhibitors at suppressing tumor growth." (PMID 31480735, 2019).
tumor (continued). "Since the effects of BET inhibitors are often through inhibition of the BET protein BRD4, we evaluated expression of hnRNPA1 and BRD4 in human tumor specimens." (PMID 31480735, 2019). "To validate the mechanisms of estradiol in vivo, we assessed the expression of hnRNPA1 and MDM2 of tumor tissues at protein levels." (PMID 28035066, 2017). "Via binding to hnRNPA1, SK was also shown to be an effective suppressor of specific post-transcriptional and ICD effects that promote tumor-immunogenicity of treated tumor cells." (PMID 27248319, 2016). "The in vivo anti-metastatic effect of tumor cell lysate (TCL) and the derived TCL-pulsed DC vaccine further supports the critical role of hnRNPA1 in the immunogenicity of TCL resulting from stimulation by SK." (PMID 27248319, 2016). "Future research could investigate the mechanisms of CAFs in other tumor types and assess the potential clinical applications of USP7, hnRNPA1, and miR-522." (PMID 40485724, 2025). "In addition, GSE29044 had more differentially expressed GRPGs between normal and tumor tissues (CS, PGK1, HNRNPA1, ADPGK, YWHAZ, PTK2, and PGAM1) than GSE42568 (CS, HNRNPA1, ADPGK, and PTK2)." (PMID 40046063, 2025). "Furthermore, ZMYND11 counteracts the HNRNPA1-driven increase in the PKM2/PKM1 ratio, thus mitigating the aggressive tumor phenotype promoted by PKM2." (PMID 39341825, 2024). "Furthermore, hnRNPA1 directly binds to 3’-untranslated VRK1 mRNA, which contributes to its translation and tumor cell proliferation." (PMID 38753965, 2024). "Top underexpressed tumor suppressor candidates such as UBXN1, HNRNPA1, PPP1R15A, and LAPTM5 may also be contributing to tumor tissue formation through inhibition of apoptosis at initial stages of cancerogenesis." (PMID 36359790, 2022). "Furthermore, AC administration suppressed the expressions of Ki-67, HMGA1, N-cadherin, and hnRNPA1 and increased the expressions of E-cadherin, GRP78, and Chop in tumor tissues (P < 0.01)." (PMID 35692504, 2022). "Moreover, in an independent dataset of Clinical Proteomic Tumor Analysis Consortium (CPTAC), HNRNPA1 protein was also overexpressed in luminal, HER2+, and TNBC tumors." (PMID 34961772, 2021). "Furthermore, HNRNPA1 is co-expressed with bromodomain and extraterminal domain protein BRD4 in human tumor samples." (PMID 32719673, 2020). "We generated three gastric fibroblast cell strains with the knockdown of USP7, hnRNPA1 and miR-522 respectively by using lenti-viruses containing shRNAs, and these fibroblast cell strains were mixed with SGC7901 cells for subcutaneous tumor implantation in mice." (PMID 32106859, 2020). "Even though Quercetin can suppress tumor development through modulation of a number of signaling pathways, we show that Quercetin enhances the anti-tumor effects of JQ1 in part by suppressing hnRNPA1." (PMID 31480735, 2019). "To investigate whether SK-induced ICD is via the suppression of hnRNPA1 activity, we compared the change in expression patterns of specific ICD markers, including HSP70 and HMGB1, in response to SK treatment in tumor cells." (PMID 27248319, 2016). "The authors conclude that tumor environmental factors such as hypoxia and nutrient deprivation activate HIF1A signaling for the maturation of AEP, which, in turn, cleaves DDX3X to promote its sequestration in the nucleus, thus initiating a nuclear DDX3X/hnRNPA1–dependent AS program in tumor cells." (PMID 38299588, 2024). "Mechanistically, a study revealed that KRASG12D induced HnRNPA1 hyperactivation, interacted with TSG101, and enhanced hnRNPA1 packaging and delivery via EVs, which were internalized by human endothelial lymphocytes in the tumor microenvironment and promoted lymph node metastasis." (PMID 37152291, 2023).
tumor (continued). "While, knocking down hnRNPA1 through the transfection of hnRNPA1 siRNA led to the increase of MDM2 at both protein level and gene level In vivo experiment, subcutaneous injection with estradiol every two days near the tumor at doses of 2.5mg/kg/d suppressed tumor growth and reduced MDM2 expression." (PMID 28035066, 2017). "Using real-time PCR and Western-blot analysis we analyzed expression of seven splicing factors belonging to SR proteins family (SF2/ASF, SC35, SRp20, SRp75, SRp40, SRp55 and 9G8), and one non-SR factor, hnRNP A1 (heterogeneous nuclear ribonucleoprotein A1) in 38 pairs of tumor-control ccRCC samples." (PMID 21082031, 2010). "In addition, chemotoxicity affects tumor growth and attenuates cisplatin chemotherapeutic efficacy by boosting miR-522 release from CAFs through triggering the USP7/hnRNPA1 pathway, whereas preventing miR-522 secretion could inhibit tumor growth and enhance sensitivity to cisplatin." (PMID 37213276, 2023). "Moreover, by considering the apparently non-essential role of hnRNPA1 in OXP-induced ICD activities, our results also suggest that hnRNPA1-targeting may not be universal for all ICD inducers with stimulatory activity on the ICD of tumor cells." (PMID 27248319, 2016). "Median levels of other SF proteins, except HNRNPA1 and SRSF7, were not significantly different based on tumor status, lymph node metastasis, TNM stage, or aneuploidy status in both gastric and CR adenocarcinoma." (PMID 27282379, 2016). "Finally, these genes were overlapped with the upregulated DEGs from the two GSE9782 datasets, resulting in 7 tumor stemness-related genes, including NONO, CBX3, SLC25A3, PTPRG, NPM1, HINT1, HNRNPA1." (PMID 41050668, 2025). "Importantly, hnRNPA1 performed better diagnostically at (a) identifying KRASG12D PDAC and (b) distinguishing between LN-positive and -negative disease, compared with classic tumor biomarkers carcinoembryonic antigen CEA0 and carbohydrate antigens CA19-9 and CA72-4." (PMID 35838046, 2022).